PTPRU (protein tyrosine phosphatase receptor type U)
Description:
Tyrosine-protein phosphatase which dephosphorylates CTNNB1. Regulates CTNNB1 function both in cell adhesion and signaling. May function in cell proliferation and migration and play a role in the maintenance of epithelial integrity. May play a role in megakaryocytopoiesis.
Synonyms: R-PTP-U; PCP-2; PTP-J; hPTP-J; PTP-RO; R-PTP-psi; FMI; PTPRO; PTP; PTP-PI; PTPPSI; PTPU2
Tractability: Antibody: UniProt places it where antibodies can reach, with high confidence; its Gene Ontology location is reachable by antibodies, with high confidence; UniProt predicts a signal peptide or a membrane-spanning region. PROTAC: ubiquitination databases record sites on it.
Target class: Enzyme; Protein Phosphatase; Receptor tyrosine-protein phosphatase; Tyrosine protein phosphatase; Phosphatase
Gene: Protein-coding gene on chromosome 1 (29,236,505 to 29,326,813, forward strand). Ensembl gene ENSG00000060656.
Subcellular location: Cell junction; Cell membrane
Pathways (Reactome):
Signal Transduction: Signaling by SCF-KIT
Gene Ontology:
Molecular function: beta-catenin binding; protein binding; protein tyrosine phosphatase activity; transmembrane receptor protein tyrosine phosphatase activity
Biological process: negative regulation of canonical Wnt signaling pathway; negative regulation of cell migration; negative regulation of cell population proliferation; positive regulation of cell-cell adhesion mediated by cadherin; protein dephosphorylation; protein localization to cell surface; cell adhesion; cell surface receptor protein tyrosine phosphatase signaling pathway; neuron projection development; signal transduction; animal organ regeneration; response to glucocorticoid
Cellular component: cell-cell junction; plasma membrane; anchoring junction; membrane
Genetic constraint (gnomAD): Loss-of-function variants: 69 observed, 160.72 expected, observed/expected ratio (o/e) 0.43, 90% interval 0.35 to 0.52. The upper end of that interval is the gene's LOEUF score, 0.52, which puts it in group 2 of 6, group 1 being the genes least tolerant of losing a copy. Missense variants: 1,657 observed, 1,975.9 expected, observed/expected ratio (o/e) 0.84, 90% interval 0.81 to 0.87. Synonymous variants: 793 observed, 798.64 expected, observed/expected ratio (o/e) 0.99, 90% interval 0.94 to 1.05.
Homologues: Orthologues: macaque PTPRU (99% identical), chimpanzee PTPRU (99% identical), pig PTPRU (98% identical), dog PTPRU (97% identical), guinea pig PTPRU (97% identical), mouse Ptpru (95% identical), rat Ptpru (95% identical), rabbit PTPRU (88% identical), zebrafish ptprub (75% identical), zebrafish ptprua (72% identical), tropical clawed frog ptpru (68% identical). Paralogues in human: PTPRK (60% identical), PTPRM (54% identical), PTPRT (52% identical), PTPRF (28% identical), PTPRS (28% identical), PTPRD (28% identical), PTPRZ1 (23% identical), PTPRG (21% identical), PTPRC (19% identical), PTPRB (18% identical), PTPRA (16% identical), PTPRE (15% identical), and 23 more.
Diseases named in the same sentence as PTPRU in open-access papers:
PTPRU is named in the same sentence as 15 diseases in open-access papers, as found by Europe PMC text mining. Sharing a sentence is not in itself a finding about the gene and the disease. The quoted sentences say what the papers report.
lung cancer (6 papers, 2015 to 2025). A malignant neoplasm involving the lung. "Scientists have demonstrated that abnormal expression of hsa-miR-125a-5p is involved in lung cancer metastasis by targeting PTPRU and this miRNA is a predictor for patients with advanced NSCLC." (PMID 36011391, 2022). "miR-574-5p also participates in the promotion of metastasis and invasion of lung cancer through PTPRU (protein tyrosine phosphatase, receptor type U) and TLR9 signaling." (PMID 32574204, 2020). "Previous research reported that miR-574-5p enhanced tyrosine phosphorylation of β-catenin by repressing PTPRU expression in vitro and promotes the migration and invasion of nonsmall cell lung cancer (NSCLC) cells." (PMID 32906628, 2020). "In miRNA-targeted genes of READ, ZFPM2 was recommended as a diagnostic biomarker for malignant pleural mesothelioma and PLXNA1 and PTPRU were related to lung cancer or colon cancer." (PMID 32964043, 2020). "PTPRU was also reported to be significant down-regulatedin lung cancer cell lines." (PMID 26587830, 2015). "CPT modulates miR-574-5p expression via promoter methylation and targets protein tyrosine phosphatase receptor type U (PTPRU) to influence TLR9 signaling, thereby affecting apoptosis and improving lung cancer." (PMID 41154678, 2025).
colon cancer (2 papers, 2016 to 2020). "Protein tyrosine phosphatase receptor type U (PTPRU), also known as Purkinje cell protein 2 (PCP2), is a PTP that has been shown to negatively regulate the growth and migration of colon cancer cells." (PMID 27761023, 2016).
gastric cancer (2 papers, 2016 to 2020). A primary or metastatic malignant neoplasm involving the stomach. "PTPRU was involved in maintaining epithelial integrity, regulating Wnt/β-catenin signaling pathways and neurodevelopment and has been shown to act as a regulator of adhesion and proliferation in colon, breast, glioma and gastric cancer." (PMID 32906628, 2020).
behavioral disorders (1 paper, 2025). "For rs72652685, located close to the PTPRU gene, the A allele is linked to a higher risk of mental health and behavioral disorders related to stimulant use." (PMID 40002435, 2025).
E. coli infection (1 paper, 2020). "The results of this study indicated that miR-215 could regulate E. coli infection by targeting EREG, NIPAL1 and PTPRU genes." (PMID 32906628, 2020).
cancer (12 papers, 2015 to 2025). A tumor composed of atypical neoplastic, often pleomorphic cells that invade other tissues. "PTPRU, IKBKE, STYK1, and CENPO are implicated in key biological pathways relevant to cancer biology, including cell signaling, cell migration, and inflammation, further supporting their relevance in tumorigenesis." (PMID 39684488, 2024). "By inhibiting Hippo/YAP signaling, PTPRU functions as a tumor suppressant that inhibits the stemness of cancer stem cells." (PMID 36081904, 2022). "In gastroenteric cancer, Hippo/YAP signaling transduction is also inhibited by PTPRU, leading to the attenuation of cancer." (PMID 34568330, 2021). "Together with its subfamily members PTPRU and PTPRK, they are amongst the most frequently mutated PTPs in a number of cancer types." (PMID 27586084, 2016). "Thus, repressed expression of PTPRU may cause increased mobility among cancer cells." (PMID 26587830, 2015). "However, the function of PTPRU varies between different cancers." (PMID 26587830, 2015). "Overlap of essential E‐boxes for four cancer cell lines revealed only three (1%) common E‐boxes: chr1_BS1363_CACAATG with neighbor genes MECR and PTPRU, chr11_BS79_CGCGTG localized near RPLP2 and PIDD1, and chr18_BS691_CATGTG adjacent to RBFA and TXNL4A." (PMID 37519063, 2023). "Among the numerous targets predicted, 2 genes, namely, PTPRU and EPAS1,were previously reported to be involvedin cancer metastasis." (PMID 26587830, 2015). "Meanwhile, protein tyrosine phosphatase receptor type U (PTPRU), also known as Purkinje cell protein 2 (PCP2), has been shown to function as a regulator of adhesion and proliferation in certain cancer cell types." (PMID 26587830, 2015). "However, up to now, there is no report about the relationship between PTPRU and cancer prognosis." (PMID 27761023, 2016).
tumor (5 papers, 2015 to 2024). "PTPRU has beenidentified as an oncogene in gastric cancer as well as in glioma, but it has also been confirmed as a tumor suppressor in colon cancer due to its dephosphorylation of β-catenin and inhibition of subsequent downstream signaling." (PMID 26587830, 2015).
PTPRU also shares sentences with these, for which no sentence is quoted: glioma (2 papers); Anxiety (1); Autoimmunity (1); bacterial infection (1); depression (1); malignant pleural mesothelioma (1); non-small cell lung carcinoma (1); schizophrenia (1).